KIT (KIT proto-oncogene, receptor tyrosine kinase)
Diseases named in the same sentence as KIT in open-access papers (continued):
Sharing a sentence is not in itself a finding about the gene and the disease.
melanoma (continued). "It appears that the mutational landscape of mucosal melanoma points out to a distinct pattern between the upper and lower regions of MM commitment with SF3B1 and KIT presenting higher mutation rates than the common drivers of cutaneous melanomas, namely BRAF and NRAS." (PMID 31949210, 2020). "Additionally, mutations were common in melanoma, including BRAF (50%), NRAS (30%), MAP2K1 (6%), and KIT (2.6%)." (PMID 33133157, 2020). "Unfortunately, most of the large melanoma cohorts on KIT mutation did not report completely the exon involvements." (PMID 31848942, 2020). "A recent study also found that in patients without lymph node metastasis at the initial diagnosis, the expression of KIT was significantly higher than that of patients with lymph node metastasis, indicating that melanoma with missing KIT expression is more likely to progress and metastasize." (PMID 32894090, 2020). "In this study, we highlighted the potential role of CXCL8, THBS1 and KIT in melanoma metastasis." (PMID 32894090, 2020). "We showed that KIT was constitutively phosphorylated in the three melanoma cell lines." (PMID 32344828, 2020). "Although we did not directly show that blocking the FGF2/FGFR axis had an effect on tumor growth, it was recently shown that ponatinib, a dual KIT and FGFR inhibitor, caused much stronger inhibition of KIT-mutation-bearing melanoma in vivo than imatinib agreeing with our results." (PMID 32344828, 2020). "We and others have shown that KIT is a bona fide oncogene in a subset of melanoma, driving tumor cell proliferation, progression, and migration through the constitutive activation of downstream signaling cascades, therefore demonstrating that KIT is a therapeutic target in these tumors." (PMID 32344828, 2020). "This differs from mechanisms of resistance observed in melanoma driven by KIT alterations where, thus far, no such secondary mutations have been observed." (PMID 32344828, 2020). "KIT mutant was reported to require HIF-1α to transform melanocytes into melanoma cells." (PMID 33133157, 2020). "The PATH panel was designed to cover most targetable mutations and amplifications for lung cancer, colorectal cancer, melanoma, and GIST for first line treatment options, as well in the setting of therapy resistance (e.g. EGFR, ALK and KIT gatekeeper mutations)." (PMID 32264863, 2020). "Moreover, in acral and mucosal melanoma, in which KIT alterations are frequent, only 20–30% of patients respond to anti-PD-1 immunotherapy." (PMID 32344828, 2020). "Indeed, the HGF-MET axis has been described as a mechanism of de novo resistance in a patient with a KIT-mutant melanoma." (PMID 32344828, 2020). "However, KIT-mutant melanoma tumors tend to show a de novo resistance in most cases and a limited duration of response when response is achieved." (PMID 32344828, 2020). "Concerning ctDNA molecular features, mutations in the BRAF, NRAS, KIT and TERT genes are considered melanoma-driving mutations and their detection could help to adapt the strategy for patient monitoring." (PMID 32295074, 2020). "Analysis of our patients’ tumors suggested that the FGF2 axis may also be a mechanism of resistance in KIT-mutant melanomas." (PMID 32344828, 2020). "In our study, we identified two gene expression patterns and generated an 8-gene-based (GPR87, KIT, SH3GL3, PVRL1, ATP1B1, CDAN1, FAU, and TNFSF14) gene signature that could recognize melanoma patients with a high risk of unfavorable clinical outcomes." (PMID 32411243, 2020). "Despite the presence of the same mutation, it is unclear why there is such a difference in response between KIT-mutant melanoma and GIST, suggesting that there may be other pathways involved in this treatment resistance." (PMID 32054078, 2020). "In one case of malignant PEComa, BRAF and KIT mutations were found to be negative, with melanoma excluded." (PMID 33061792, 2020).
melanoma (continued). "The study in this report indicates that the FGFR axis may be a mechanism of resistance in KIT-mutant melanomas through activation of the MAPK pathway." (PMID 32344828, 2020). "Our signature consists of diverse genes comprising protective (ATP1B1, CDAN1, FAU, and TNFSF14)) and risky (GPR87, KIT, SH3GL3, and PVRL1), which could be considered gene-related protective and risk patterns in melanoma." (PMID 32411243, 2020). "Another targeted therapy utilized for the treatment of melanoma are KIT inhibitors." (PMID 33256089, 2020). "The DEGs that associated with other genes in this network are KIT, CDKN1C, and TYRP1, suggesting these three DEGs may affect melanoma, in which TYRP1 was both a DEG and a melanoma gene." (PMID 32015692, 2020). "BIM expression may therefore serve as a potential biomarker useful for predicting response to KIT inhibition in melanoma." (PMID 32344828, 2020). "Imatinib and nilotinib are the main c-KIT inhibitors that have been studied in melanoma." (PMID 32429485, 2020). "Finally, eight genes (GPR87, KIT, SH3GL3, PVRL1, ATP1B1, CDAN1, FAU, and TNFSF14) were identified to be closely associated with the OS in melanoma." (PMID 32411243, 2020). "About 22% of triple-wild-type melanomas contain KIT aberrations." (PMID 32344828, 2020). "At the cellular level, we observed that the exposure of BRAF-mutant melanoma cells to 1 resulted in a pronounced down-modulation of KIT, which was paralleled by the shutdown of the RAS/RAF/MAPK and PI3K/AKT signaling pathways, both at the transcriptomic and post-translational levels." (PMID 31635389, 2019). "KIT mutations are more frequently detected in mucosal (about 11.5% of cases) and acral (10.8% of cases) melanomas while they have not been reported in uveal melanoma." (PMID 31683701, 2019). "In patients with melanoma harboring KIT mutation in exon 11 or 13, KIT inhibitors can be a treatment option; however, none of them have been approved in Japan." (PMID 30675668, 2019). "Furthermore, KIT mRNA expression was significantly higher in patients showing clinical benefit from the combined therapy, emphasizing the tumor-suppressor role of KIT already described within the context of BRAF-mutant melanoma." (PMID 31426590, 2019). "At present, imatinib is likely most effective in patients with melanoma harboring KIT mutations (exon 11 or 13); however, the response rate is not that high, and a durable response seems not to be expected." (PMID 30675668, 2019). "At the cellular level, the exposure of BRAF-mutant melanoma cells to the compound resulted in a marked down-modulation of KIT, which was paralleled by the shutdown of the MAPK and PI3K/AKT signaling pathways, both at the transcriptomic and post-translational levels." (PMID 31635389, 2019). "Recent evidence has indicated that the transmembrane receptor tyrosine kinase c-KIT may also be an attractive therapeutic target in melanoma." (PMID 31635389, 2019). "Thus, constitutively active mutations of KIT allow host cells to autonomously proliferate, resulting in the development of AML, MCL, GIST, germ cell tumors, and melanoma." (PMID 31484543, 2019). "Both SF3B1 (50%) and KIT (67%) mutations were most frequently mutated in tumors of female genital origin and anorectal region (33.3% for SF3B1 and KIT) compared to a single SF3B1 mutant conjunctival melanoma in the upper body sites." (PMID 30847022, 2019). "For example, despite an absence of BRAF and lower abundance of RAS and KIT mutations in canine versus human mucosal melanoma, these tumors display likely MAPK activating events in 35% of cases." (PMID 30188888, 2018).
melanoma (continued). "Moreover, there was an increase in KIT protein expression in mucosal melanomas, which supports their role in the progression of this melanoma subtype." (PMID 29796159, 2018). "Melanomas with aberrations of the KIT genes might represent another subgroup, which benefit from a therapy targeting the gene product c-Kit." (PMID 29492238, 2018). "Mutations of the main RTKs transducer—RAS/BRAF—are events more frequent than mutations in RTKs, yet, mutated forms of RTK genes including KIT, ERBB1-4, PDGFR, the EPH and FGFR families, and others are known to govern abnormal signaling driving aberrant growth and survival of melanoma cells." (PMID 29946532, 2018). "On the other hand, c-KIT expression is lost in breast cancer and melanoma." (PMID 28301608, 2017). "Among vulvar melanomas, approximately 20% contain KIT mutations, a number in line with the rate seen among other nonvulvar melanoma subtypes." (PMID 28428884, 2017). "Spitz tumors generally lack mutations in oncogenes classically associated with melanoma, such as NRAS, KIT, GNAQ, and GNA11, though distinct histopathologic forms have been found to harbor BRAFV600E and HRAS mutations, and suggest a role for activating kinase pathways in tumorigenesis." (PMID 28895885, 2017). "Existing literature reports KIT activation in 15-39% of mucosal melanomas." (PMID 28380455, 2017). "Mutations in BRAF, NRAS, or KIT are present in more than 60% of melanoma cases, but a useful blood-based biomarker for the clinical monitoring of melanoma patients is still lacking." (PMID 28484715, 2017). "Finally, other less frequently mutated melanoma genes (KRAS, HRAS, KIT, GNAQ, GNA11) were enriched in tumors wild‐type for BRAF, NRAS, and NF1." (PMID 28267273, 2017). "Furthermore, for mutated genes normally related to non‐sun‐induced melanomas (KIT, GNA11, GNAQ), we found that KIT and GNA11 were enriched in the triple‐wild‐type group (FDR < 0.001 or 0.01, respectively)." (PMID 28267273, 2017). "Authors have demonstrated in melanomas wild type for NRAS and BRAF, that activating constitutively KIT mutations may be functionally equivalent to constitutive activation of the RAS-RAF-MEK-ERK pathway due to NRAS or BRAF." (PMID 26863566, 2016). "Our work suggests that KIT inhibition might help to target migratory active, KIT mutant melanoma cells, thus representing a potential strategy to reduce spread and local recurrence." (PMID 27322141, 2016). "Similarly, KIT mutant human melanoma lines were able to populate a larger area in a 3D in vitro skin model compared to KIT wild type and BRAF mutant lines." (PMID 27322141, 2016). "In addition, we evaluated the impact of KIT inhibitors to reduce migration of KIT mutant melanocytes and regress intraepidermal melanoma progression." (PMID 27322141, 2016). "The intracellular regions are either GIST, AML or melanoma specific, or a combination of two of the three cancer types, but interestingly KIT does not seem to harbor a ubiquitously mutated region." (PMID 27150584, 2016). "This study investigated the use of targeted drugs after OncoFOCUSTM+KIT screening in patients with malignant melanoma, non-small cell lung cancer and metastatic colorectal cancer, and then audited the results against the National Comprehensive Cancer Network (NCCN) guidelines." (PMID 28163892, 2016).
melanoma (continued). "In addition, in vivo experiments harnessing a mouse xenograft model of early melanoma development demonstrated rapid lateral migration of KIT mutant cells compared to respective controls." (PMID 27322141, 2016). "Only one germline mutation of KIT, V559A, has been described in melanoma so far, other patients in the same family carrying the same germline mutation of KIT did not develop melanoma." (PMID 27777718, 2016). "The role of KIT in the development of malignant melanoma has been largely discussed." (PMID 26863566, 2016). "We found that while melanoma cell lines expressing mutant KIT migrated over 7mm away from the seeding area after 2 weeks of 3D culture, BRAF mutant melanoma cells and wild type melanocytes only migrated less than 4mm from the seeding site at 2 weeks (2-sided student t-test; p<0.05)." (PMID 27322141, 2016). "Still, our results indicated that KIT inhibitors might help to reduce local recurrence of KIT-activated melanoma by reducing migration in addition to reducing viability and might thus be considered for the early treatment of these tumors." (PMID 27322141, 2016). "KIT aberrations are also frequent in acral melanomas and cutaneous melanomas arising over chronically sun-damaged skin, prompting clinical trials of KIT inhibitors in KIT-mutant melanoma." (PMID 27502704, 2016). "In addition, we also demonstrated a novel inhibitory function for the pharmacological agents imatinib, dasatinib and nilotinib, currently used to treat metastatic KIT mutant melanoma patients, to block this migration." (PMID 27322141, 2016). "Secondary c-Kit mutations confer acquired resistance to RTK inhibitors in c-Kit mutant melanoma cells, and KIT copy number gain may be a mechanism by which melanomas acquire therapeutic resistance to imatinib." (PMID 25605243, 2015). "In total, only 9.6% of all cases in the cohort were negative for either of the genetic changes in BRAF, NRAS, NF1 and KIT, indicating that the majority of melanomas could potentially have activated MAPK pathway through these genetic alterations." (PMID 25909218, 2015). "A variety of spindle cell tumors exhibit KIT positivity, including mesothelioma, leiomyosarcoma, clear cell sarcoma, rhabdomyosarcoma, synovial sarcoma, angiomyolipoma, bladder urothelial carcinoma, and malignant melanoma." (PMID 24938355, 2014). "Ligand-blockage and selective cytoplasmic expression of KIT in melanoma cells could be excluded in the present study." (PMID 24489649, 2014). "Activating KIT mutations have been identified in some melanoma subtypes (mucosal, acral and non-sun-exposed), and FGF receptor (FGFR)-1 mutations have been sporadically found in melanoma." (PMID 24920406, 2014). "An alternative explanation may be that epigenetic mechanisms critical to melanoma-initiation automatically lead to silencing of the KIT gene." (PMID 24489649, 2014). "KIT is one of the major targets of imatinib; mutations of KIT predict the efficacy of the drug in gastro intestinal stromal tumors (GIST), but also in melanoma and thymic carcinoma." (PMID 25174682, 2014). "The present study also shows that somatic activating BRAF, RAS, GNAQ, GNA11 and KIT mutations, frequently observed in human melanomas, are not required for melanoma development in Grey horses." (PMID 25413220, 2014). "Furthermore, other mutations, namely, N-RAS, KIT, and GNAQ, should be sequenced according to distinct melanoma specific subtypes and clinical aspects." (PMID 24591764, 2014). "Many pigmentation genes linked to melanoma in recent GWAS such as TPCN2, ASIP, KIT, NCKX5, TYR, IRF 4, OCA2 and TYRP1 have been linked to melanoma and some of them like MC1R have dual roles in pigmentation and immune responses but many other functions of these genes remain to be discovered." (PMID 23796690, 2013). "KIT is expressed in more than one-half of early-stage malignant melanomas." (PMID 24416617, 2013).
melanoma (continued). "At least 6 genes have been shown to be recurrently mutated in melanoma, including the serine-threonine kinase encoded by BRAF; the receptor tyrosine kinase encoded by KIT; the GTP-binding proteins encoded by NRAS, GNA11, and GNAQ; and the WNT signaling pathway component encoded by CTNNB1." (PMID 22536370, 2012). "MITF knockdown also reduced the expression of KIT in MALME-3M melanoma cells." (PMID 22570637, 2012). "In addition to BRAF inhibitors, patients are directed to trials for KIT mutations, GNAQ/11 mutations in uveal melanoma, and even NRAS mutant melanoma." (PMID 22536370, 2012). "The CTC analysis also has potential benefits in terms of treating KIT mutant melanomas." (PMID 22281663, 2012). "Among the first 150 melanomas genotyped with informed consent (from 07/08/2010 to 12/13/2010), 90 (60%) had at least one mutation, including 57, 23, 6, 3, and 2 mutations in BRAF, NRAS, GNAQ, KIT, and CTTNB1, respectively." (PMID 22536370, 2012). "We report here development, validation, and implementation of an assay designed to simultaneously detect 43 common somatic point mutations in 6 genes (BRAF, NRAS, KIT, GNAQ, GNA11, and CTNNB1) potentially relevant to existing and emerging targeted therapies specifically in melanoma." (PMID 22536370, 2012). "KIT mutations have so far been found in a small subgroup of melanomas, in particular acral or mucosal tumors that are not related to sun exposure." (PMID 22007305, 2011). "As that both c-KIT and Mitf are essential factors in the development of melanocyte and melanoma and the role they play in related pathogenesis, it is of importance that the additional mechanisms and pathways that are controlled by c-KIT and regulate Mitf are identified." (PMID 21887372, 2011). "However most of these studies have been conducted on small patient samples and larger numbers, as well as consecutive patient-studies, will be needed to determine more accurate incidences of c-KIT in various types of melanoma." (PMID 21479172, 2011). "The only responder in this trial had very high KIT protein expression, supporting the hypothesis that c-KIT aberrant melanomas are responsive to c-KIT inhibitors such as Gleevec." (PMID 21479172, 2011). "While there is evidence that the KIT gene is dependent on direct stimulation by the Transcription Factor Activator Protein 2 alpha (TFAP2A) in melanoma, analyses of mutant model organisms indicate a more complex regulatory scenario within embryonic melanocytes." (PMID 20862309, 2010). "Activating KIT mutations are typically seen in mucosal and AL melanoma subtypes (5-20% of cases) but not in cases arising from chronic sun damage." (PMID 19949544, 2009). "KIT mutations are mutually exclusive with BRAF and NRAS, and may identify a subset of melanoma that preferentially respond to the KIT inhibitors such as imatinib (Gleevec) or sorafenib." (PMID 19949544, 2009). "There are also regulatory changes in KIT expression during melanoma progression." (PMID 19949544, 2009). "Melanomas also harbor mutations that promote the malignant phenotype, such as in BRAF, CDKN2A, PTEN, CTNNB1, NRAS, PIK3CA and KIT, but except for BRAF (∼50%) and common loss of CDKN2A, these mutations exist in a minor portion of melanoma specimens (10% or less)." (PMID 19234609, 2009). "c-KIT protein expression could be detected in 18 out of 18 (100%) mucosal melanomas located in the head/neck area, 7 out of 8 (86%) in the anal/rectal tract, 8 out of 11 (73%) in the genitourinary tract and 2 out of 2 (100%) in other locations." (PMID 19018266, 2008). "In conclusion, KIT mutations can be found in a subset of patients with mucosal melanomas irrespective of the location of the primary tumour." (PMID 19018266, 2008). "This suggests that c-KIT might be of pathogenetic relevance and therefore a therapeutic target in these subtypes of melanoma." (PMID 19018266, 2008).